MIR1302-11 (microRNA 1302-11)
Synonyms: hsa-mir-1302-11
Gene: MicroRNA gene on chromosome 19 (71,973 to 72,110, forward strand). Ensembl gene ENSG00000283801.
Gene Ontology:
Biological process: miRNA-mediated post-transcriptional gene silencing
Homologues: Paralogues in human: MIR1302-10 (100% identical), MIR1302-2 (100% identical), MIR1302-9 (100% identical).